RAC1 (Rac family small GTPase 1)
Diseases named in the same sentence as RAC1 in open-access papers (continued):
Sharing a sentence is not in itself a finding about the gene and the disease.
lung cancer (continued). "The tumor volumes of the Rac1 knockdown group on the 15th and 24th days after tumor-bearing were significantly smaller than those of the control group (P < 0.05), indicating that the growth of mouse lung cancer cells was significantly inhibited by Rac1 knockdown." (PMID 35031595, 2022). "The poor early surgical prognosis of some patients with nonsmall cell lung cancer is related to the Rac1 upregulation, which may be related to the fact that the high expression of Rac1 in nonsmall cell lung cancer tumor stem cells can enhance the malignant behavior of tumor cells." (PMID 35847360, 2022). "Subsequently, further to verify whether RAC1 signaling pathway was involved in the IR-triggered EMT in lung cancer cells, we detected the expression of RAC1 signaling pathway molecules in both the knockdown and overexpression of RAC1 on EMT in IR -treated and untreated cells." (PMID 32411607, 2020). "Thus, we raised the possibility that RAC1 might be an important regulator in the process of IR-induced EMT in lung cancer." (PMID 32411607, 2020). "However, the role of RAC1 in lung cancer radiotherapy is poorly understood." (PMID 32411607, 2020). "Previous study suggested that up-regulated RAC1 by IR may promote carcinogensis of lung cancer." (PMID 32411607, 2020). "However, an understanding of the GEFs that activate it to drive metastasis in lung cancer, and the mechanism by which these GEFs are facilitating the activation of Rac1, could provide novel opportunities for the development of lung cancer therapeutics." (PMID 32158759, 2020). "Moreover, EHop-016, a small molecule inhibitor of RAC1, as an adjuvant could improve the Taxol monotherapy against lung cancer cells in vitro." (PMID 31779616, 2019). "However, it is worth noting that lung cancer patients with normal or low copy number of RAC1 tended to have a higher expression of LCAT1 that could potentially drive the expression of RAC1." (PMID 31779616, 2019). "Therefore, we assumed that LCAT1 could modulate RAC1 mRNA level by competitively sponging miRNA-4715-5p, thereby enhancing lung cancer cell proliferation and invasion." (PMID 31779616, 2019). "Therefore, targeting at Rac1 may be considered as a promising therapeutic approach for the treatment of advanced lung cancer." (PMID 27556698, 2016). "Recent findings suggest that the intracellular mature form of IL-37 can block the activation of Rac1 and its downstream signaling by binding to the Rac1 CAAX motif, thus suppressing the migratory behavior of lung cancer cells." (PMID 41293155, 2025). "In lung cancer and ovarian cancer, RCC2 suppresses cell apoptosis and enhances the sensitivity of chemotherapy drugs via activating Rac1/JNK pathway." (PMID 38993556, 2024). "The treatment of lung cancer cell lines with cetuximab resulted in decreased expression of TIAM1 and reduced RAC1 activation." (PMID 39001533, 2024). "RAC1 accumulation in the nuclei has been found in PC3, LM4175 lung carcinoma and OCI-AML3 acute myeloid leukaemia cells lines." (PMID 40396280, 2024). "Luteolin repressed cell metastasis in lung cancer via Src/FAK and its downstream Rac1, Cdc42, and RhoA pathways." (PMID 36874921, 2023). "Among the commonly deregulated genes, we found a significant up-regulation of the Rac Family Small GTPase 1 (RAC1) gene and neuropilin 2 (NRP2), which are involved in tumor migration and invasion in different tumors including lung cancer." (PMID 35884472, 2022). "In the present study, we found that the BAI1/Rac1 signaling pathway positively controls Notch1 signaling, leading to WISP-1 secretion from and efferocytosis of apoptotic lung cancer cells by CAFs." (PMID 36241874, 2022). "More recently, Ciarlantini and colleagues identified a new family of chemical inhibitors against Rac1–GEF interaction that exhibited significant anti-proliferative activities in vitro and in a lung cancer animal model." (PMID 36077697, 2022).
lung cancer (continued). "In lung cancer and prostate cancer, the low expression of HACE1 can make Rac1 overactive, which is related to the shortened survival time of tumor." (PMID 34079763, 2021). "In the present study, we found that IR promoted lung cancer cell EMT in the process, accompanied with an up-regulation of RAC1, PAK1, p-PAK1, LIMK1, p-LIMK1, Cofilin, p-Cofilin in these cells." (PMID 32411607, 2020). "However, unlike KRAS, point mutations in RAC1 are rare in lung cancer." (PMID 32158759, 2020). "One interesting example is the activation of rRNA synthesis and tumorigenesis in the nucleolus of lung cancer cells by the GEF Ect2, thus implicating Rac1 in ribosomal biogenesis, a process associated with tumor growth, EMT and metastasis." (PMID 32158759, 2020). "Others hold MASPIN inhibits cell motility by suppressing Rac1 and PAK1 activity, promotes cell adhesion via the PI3K/ERK pathway, and suppresses survival of lung cancer cells through modulation of AKT pathway." (PMID 32391558, 2020). "Pancreatic adenocarcinoma tissue microarrays (TMAs) were stained for MMP3, Rac1b (a tumorigenic splice isoform of Rac1 previously shown to be upregulated by MMP3 in pancreas, breast, and lung cancers), collagen I, and H&E." (PMID 26807201, 2015). "In lung cancer cells, phosphorylated Rac1 GEF VAV2 colocalizes with FAK at focal adhesion sites and activates Rac1 signaling, allows FAK phosphorylation, and promotes cell attachment in vimentin-expressing cells." (PMID 25965826, 2015). "c-MET is a receptor tyrosine kinase abnormally activated in many cancer types, such as renal, liver, head and neck, gastroesophageal, breast, and lung cancer, and activates several intracellular signaling pathways including RAS-MAPK, PI3K-AKT, RAC1, and PAK to promote the progression of cancers." (PMID 35558557, 2022). "Previous work demonstrated that RAC1 is critically involved in NSCLC migration and lung CSC formation and that RAC1 served as a useful therapeutic target by inhibiting tumour initiation and metastasis of CSCs in lung cancer." (PMID 34059086, 2021). "Similar to most members of the Rho family of guanine-nucleotide binding proteins, Rac1 is a small GTPase (Mw ∼ 21 kDa) that cycles between active GTP-bound and inactive GDP-bound states, and is the most prominently expressed Rac GTPase in lung cancer." (PMID 32158759, 2020). "RAC1 signalling was shown previously to be a key mediator of cancer migration modulating F-actin organization in colorectal cancer, while CAV1 has been demonstrated to promote cancer growth and migration in lung cancer." (PMID 33050615, 2020). "There was a weak positive correlation between LCAT1 and RAC1, and a negative correlation between miR-4715-5p and LCAT1/RAC1 in the lung cancer tissues." (PMID 31779616, 2019). "In H460 lung cancer cells, TCS promoted migration and invasion through focal adhesion kinase/ATP-dependent tyrosine kinase (FAK/Akt) and Ras-related C3 botulinum toxin substrate 1 (Rac1)." (PMID 31191794, 2019). "In summary, our studies found that RCC2 is often overexpressed in lung cancer and ovarian cancer, and RCC2 expression in cancer cells altered their sensitivity to drug-induced cell death, probably because of its interaction with cellular Rac1 activity." (PMID 29321004, 2018). "We explored here whether the expression of RBD-mutant p110α might affect the activation of RAC1, as measured by guanosine triphosphate (GTP) loading, upon EGF stimulation in EGFR-mutant human lung cancer cell lines." (PMID 30590030, 2018). "It revealed that Rac-1 was activated in HUVECs after co-culture with CL1-5, and this might contribute to the increasing motility of HUVECs after interaction with lung cancer cells." (PMID 28173828, 2017). "Suppression of CNTN1 expression abolished the ability of lung cancer cells to invade and metastasize by activating RhoA, but not Cdc42 or Rac1, suggesting that CNTN1 is a key regulator of invasion and metastasis in lung adenocarcinoma." (PMID 22580838, 2012).
lung cancer (continued). "Here, we show that the RAC1-selective guanine nucleotide exchange factor T cell invasion and metastasis-inducing protein 1 (TIAM1) promotes cell migration and invasion in the most common subtype of lung cancer, non-small-cell lung cancer (NSCLC), through an unexpected nuclear function." (PMID 37748077, 2023). "In cases of lung cancer, KIF4A was reported to promote cell proliferation and migration and inhibit apoptosis in LUAD cell lines, whereas KIF18B was suggested to promote LUAD cell proliferation, migration, and invasion via the Rac1/Akt/mammalian target of rapamycin (mTOR) signaling pathway." (PMID 36499051, 2022). "Interestingly, using a phosphoproteomic screen in lung cancer cells, the Rac1 guanine nucleotide exchange factor (GEF) VAV2 was identified as a downstream target of vimentin which induces VAV2 phosphorylation and the localization to FAs where it activates Rac1." (PMID 35990612, 2022). "In addition, RT induces expression of Ras related C3 botulinum toxin substrate 1 (RAC1), a member of the Rho family GTPase which promotes cell division via cell cycle, and enhances radioresistance via p21-activated kinase 1 (PAK1)-LIM kinase 1 (LIMK1)-Cofilins signaling in lung cancer." (PMID 33419318, 2020). "Another previous study exploring the interaction partners of ARHGEF39 identified RAC1, but not RHOA (or CDC42) in a pulldown assay from lung cancer cells overexpressing ARHGEF39." (PMID 35959104, 2022). "There was a weak positive correlation between LCAT1 and RAC1, and a negative correlation between miR-4715-5p and LCAT1/RAC1 in lung cancer tissues." (PMID 31779616, 2019).
glioma (91 papers, 2008 to 2026). A benign or malignant brain and spinal cord tumor that arises from glial cells (astrocytes, oligodendrocytes, ependymal cells). "The expression of the Rac1 mRNA in low-grade gliomas (LGG, with IDH1 mutated) and GBM was analyzed using the GTEx and TCGA databases." (PMID 36230732, 2022). "Rac1 has long been associated with tumor progression and plays a key role in glioma’s infiltrative and invasive nature." (PMID 36230732, 2022). "Our study also indicates a novel therapeutic strategy for IDH1-mutated gliomas by targeting the small GTPase, Rac1." (PMID 32224866, 2020). "The impact of RhoA and Rac1 on glioma migration is in good agreement with the observation of an increased FAK activation, negatively regulating RhoA and activating Rac1 in glioma, being associated with staging and a poorer prognosis." (PMID 31003495, 2019). "Inhibition of the RhoA target ROCK led to increased migration in glioma cells via an activation of Rac1 and Rac1 inhibition was associated with reduced migration and invasion." (PMID 31003495, 2019). "On the one hand, it is strongly expressed at the cell front and necessary for migration and, on the other hand, a marked activation causes an inhibition of glioma migration, via an inhibition of Rac1, and increased contractility, via larger focal adhesions." (PMID 31003495, 2019). "This view is even more challenged, as in glioma patients especially transcript variant 2 has been associated to Rac1 signaling stimulating migration and leading to a poorer outcome." (PMID 28881583, 2017). "Integrins have recently been implicated in promoting the motility of glioma cells via activation of multiple small GTPases including Rac1 and Cdc42." (PMID 26377974, 2015). "The network topology analysis performed in this study revealed a set of central nodes associated to glioma malignancy, such as Map3k14, Mapk1, Actn4, Hspa5, Atf2, Rac1,E2f1, Shc1, Pik3ca, Akt1, Vim and Egr1." (PMID 26582089, 2015). "In GBM and in experimental glioma models, the activation of Rho GTPases (such as Rac1) has been linked to increased cell invasion, pointing to these molecules as key therapeutic targets." (PMID 24939046, 2014). "It is therefore possible that deregulated E-cadherin signaling causes increased Rac1 activation and induces tumor cell growth and invasion of human glioma cells." (PMID 21060868, 2010). "In addition, TUNAR (neural differentiation-associated RNA) represses migration, and invasion of glioma cells by positively regulating miR-200a which suppresses the expression of Rac1." (PMID 31248165, 2019). "Glioma cells transfected with Rac1, p66Shc, or both were treated with varying concentrations of quercetin for different time points." (PMID 38362155, 2024). "Activation of the mevalonate pathway and Rac-1 was inhibited by statins, which led to improved survival in mouse models of glioblastoma when combined with radiation and drugs that target the glioma stem cell pool and plasticity of glioma cells." (PMID 38837899, 2024). "Studies have revealed that Ber inhibits the invasive activity of human glioma cells’ matrix metalloproteinase 9 in human glioma cells by regulating the activity of Rac1." (PMID 38741587, 2024). "Since ROS generation is primarily regulated by p66Shc-Rac1 signaling, we looked for the effect of quercetin on the migratory potential of gliomas using wound-healing assay by modulating p66Shc, Rac1, or ROS titer." (PMID 38362155, 2024). "This, in turn, was found to be dependent on its GAP domain leading to the activation of RhoA and Rac1, promoting glioma and glioblastoma cell invasiveness." (PMID 37627074, 2023). "Mechanistically, 1A-116 inhibits Ras-related C3 botulinum toxin substrate 1 (RAC1) GTPase in human glioma cells and mice." (PMID 36796229, 2023). "Sema3C signaling via this complex promotes the survival of glioma stem cells via activation of Rac1." (PMID 37627074, 2023).
glioma (continued). "This study shows the preclinical evaluation of 1A-116, a Rac1 inhibitor that showed in vitro antitumor activity on glioma cells." (PMID 36230732, 2022). "Both in LN229 and U‐87 glioma cell lines, 1A‐116 specifically inhibited Rac Family Small GTPase 1 (RAC1) activation to guanine exchange factors such as T‐lymphoma invasion and metastasis‐inducing protein 1 (Tiam1), by interacting with the Trp56 residue." (PMID 36066207, 2022). "Since Rac1 is an interesting molecular target in glioma, we assessed the effect of the 1A-116 Rac1 inhibitor on a panel of GBM cells." (PMID 36230732, 2022). "Given the marked differences between both models and that Rac1 is attractive for therapeutically targeting invasion dynamics in glioma, we further established an orthotopic intracranial LN229 mouse model to evaluate 1A-116 efficacy." (PMID 36230732, 2022). "Altogether, our study provides important evidence of 1A-116 as a signal transduction-based precision therapy for glioma and also increases the evidence of Rac1 as a key molecular target in cancer." (PMID 36230732, 2022). "Accordingly, it has been reported that TWEAK induces activation of the non-receptor tyrosine kinase Lyn and that the knockdown of the latter abrogates TWEAK-induced chemotactic migration in T98A and A172 glioma cells as well as Rac1 activation." (PMID 36339601, 2022). "Altogether, our study establishes a strong potential for clinical translation of 1A-116 as a signal transduction-based precision therapy for glioma, as well as increases the evidence of Rac1 as a key molecular target." (PMID 36230732, 2022). "We crucially identified that KIF4A drives gliomas growth by transcriptional repression of Rac1/Cdc42 to induce cytoskeletal remodeling in glioma cells." (PMID 36606197, 2022). "These key roles in malignant progression highlight Rac1 as an interesting therapeutic target in glioma." (PMID 36230732, 2022). "Rac1 is involved in stemness maintenance, tumor cell invasion, and chemoresistance, all key features in glioma behavior and disease progression." (PMID 36230732, 2022). "In human glioma cells, we have shown that Rac1 inhibition was able to promote apoptosis and inhibit invasion and the lack of Rac1 by siRNA reduced 1A-116 activity." (PMID 36230732, 2022). "In gliomas, high RAC1 expression promotes tumor migration and invasion by inducing epithelial-mesenchymal transition and increasing matrix metalloproteinase expression." (PMID 36385959, 2022). "Altogether, our study provides a strong potential for clinical translation of 1A-116 as a signal transduction-based precision therapy for glioma and also increases the evidence of Rac1 as a key molecular target." (PMID 36230732, 2022). "The apoptosis of glioma cells induced by Rac1 inhibition can be partly saved by mitogen-activated protein kinase 1, which is the activator of JNK." (PMID 34079763, 2021). "Both in LN229 and U-87 glioma cell lines, it specifically inhibited the activation of RAC1, a monomeric GTPase involved in a variety of cellular processes required for tumor progression (proliferation, migration, and cytoskeleton reorganization)." (PMID 34371781, 2021). "Semaphorin-3C (Sema 3C) is involved in promoting the survival and tumorigenicity of glioma stem cells by activating Rac1, which is related to activating Rac1-NF-κB signal." (PMID 34079763, 2021). "XIST also has oncogenic functions in glioma; it inhibits miR-137 by acting as a sponge, thereby increasing Ras-related C3 botulinum toxin substrate 1(Rac1) expression." (PMID 33980320, 2021). "LncRNA HULC accelerates the proliferation of colon cancer cells by miR-613/RTKN 28, while lncRNA Xist, as the endogenous sponge of miR-137, upregulates Rac1, which is the target gene of miR-137 and promotes the proliferation of glioma cells." (PMID 34257656, 2021).